TNF (tumor necrosis factor)
Diseases named in the same sentence as TNF in open-access papers (continued):
Sharing a sentence is not in itself a finding about the gene and the disease.
viral infection (continued). "The multiple adverse effects of TNF-α inhibition have been identified, including a two-to four-fold increased risk of active tuberculosis and other granulomatous conditions and an increased occurrence of some other serious bacterial, fungal and certain viral infections." (PMID 30732563, 2019). "The pathways associated with viral infection (Herpes simplex infection, influenza A, and hepatitis C) and host immune response (Cytokine-cytokine receptor interaction, toll-like receptor signaling pathway, TNF signaling pathway, and intestinal immune network for IgA production) were enriched." (PMID 28938587, 2017). "Many factors have been attributed to cause HIV-associated immune activation including virus infection as well as translocation of microbial products from the intestinal lumen to the systemic circulation, and the release of high levels of pro-inflammatory cytokines, such as IL-6, TNFα and type I IFN." (PMID 23593001, 2013). "Moreover, tumor necrosis factor (TNF)-α production is downregulated during viral infection, which may also lead to increased susceptibility to secondary bacterial infections." (PMID 23326226, 2013). "It is possible that chorion cells contribute to the production of MDI factor containing IL-6 and TNF-α by amniochorion tissues in response to influenza virus infection and play a pivotal role in the pathogenesis of adverse pregnancy outcomes associated with the virus infection." (PMID 22899878, 2012). "Among these, local inflammation of the olfactory epithelium following viral infection, with increased TNF-α production and IL-6 levels as regulators of apoptosis in olfactory epithelial cells, seems particularly important." (PMID 41602885, 2026). "We identified 321 up-regulated genes and 242 down-regulated genes significantly enriched in viral infection, cancer, mineral absorption, and tumor necrosis factor (TNF) signaling pathways in all kinds of cells in the EG." (PMID 41262530, 2026). "Viral infection of immune cells provokes the release of cytokines, including interleukins and TNF, which orchestrate inflammatory and immune defenses against pathogens." (PMID 41576161, 2026). "In this tissue, the viral infection triggered a localized release of TNF-alpha and IFN-gamma, culminating in NF-kB- (and possible STAT1)-induced iNOS overexpression." (PMID 41596343, 2026). "Previous studies have identified monocytes and macrophages as primary sources of IL-6, IL-10, and TNF-α during viral infections, while IL-8 is typically secreted by macrophages and endothelial cells." (PMID 41522679, 2026). "Among many cytokines, the most crucial ones in terms of viral infection are IFNs, IL-8, IL-6, IL-1, granulocyte and macrophage colony-stimulating factor (GM-CSF), TNF alpha, IL-18, IL-12, IL-2, and IL-23." (PMID 40358160, 2025). "For instance, viral infection triggers the inflammatory response, prompting the release of cytokines, such as IL-6 and TNF-α." (PMID 40970726, 2025). "Viral infections have been proposed to enhance inflammatory signaling through IL-6, TNF-α, and IFNs, all key players in joint inflammation and autoimmune progression." (PMID 40722700, 2025). "Viral diseases and other intracellular pathogens are best controlled by type 1 responses characterized by cytokines such as type 1 IFNs, IFNγ, TNFα, and IL-2 along with antibody isotypes IgG2a/c (depending on mouse strain)." (PMID 40872809, 2025). "During viral infection, pro-inflammatory cytokines (such as IL-6, TNF-α, and IFN-γ) activate and recruit immune cells (including neutrophils and monocytes) to the site of infection, mediating apoptosis and clearance of virus-infected cells." (PMID 40872846, 2025). "During bacterial or viral infections or under stress, monocytes secrete pro-inflammatory cytokines (IL-1, IL-6, TNF-α)." (PMID 39858269, 2025).
viral infection (continued). "In the context of viral infections, IL-10 exerts anti-inflammatory via reducing the production of pro-inflammatory cytokines and chemokines, including TNF-α, IL-1β, IL-6, and IL-12, etc.." (PMID 41156600, 2025). "Induced by a series of other cytokines as IL1A (IL1A fold regulation = 2.99), IL1B (IL1B fold regulation = 10.76), IL7, TNF (TNF fold regulation = 2.39), LPS or viral infections, CCL5 behaves like a proinflammatory cytokine." (PMID 40149697, 2025). "The immunoproteasome is expressed following interferon-γ (INF-γ) stimulation, tumor necrosis factor-α (TNF-α) stimulation or viral infection." (PMID 39942858, 2025). "Viral infections trigger an immune response in host cells, leading to the release of cytokines, such as IL-17, TNF, and various T helper cell types (Th1, Th2, and Th17), at 6 and 12 hpi." (PMID 40872699, 2025). "TNF plays a critical role in the control of viral infection - through the recruitment and activation of macrophages, natural killer cells, T cells, and antigen-presenting cells." (PMID 40176816, 2025). "The marked increase in cytokines such as IL-27, IFN-γ, and TNF-α indicates robust immune activation, which is crucial for combating viral infections." (PMID 41189879, 2025). "TNF is a well know key player during viral infection by regulating inflammatory responses, as well as chemoattractant of neutrophils." (PMID 41139159, 2025). "Cytokine storm has been recognized as a critical mechanism driving disease progression in various viral infections, involving excessive release of pro-inflammatory cytokines such as IL-6 and TNF-α." (PMID 40657502, 2025). "Acute infection with CHIKV was characterized by higher concentrations of IP-10/CXCL10, IFN-α, IL-6, and TNF-α, all of which are well-established markers of viral infection and inflammation." (PMID 41346606, 2025). "The viral infection group exhibited significantly increased mRNA levels of IL-6, TNFα, CXCL-2, CXCL-3, CXCL-8/IL-8, and CXCL-10 compared to the NC group." (PMID 40872743, 2025). "TNF is an important cytokine of the innate immune response and is produced in fish in the early stages of viral infection in response to the nuclear factor-κB (NF-κB) inflammatory pathway." (PMID 40431669, 2025). "TNF-α, IL-1, and IL-6, which are key pro-inflammatory cytokines released by the host during viral infection, were significantly upregulated (fold change >20 compared to the PBS group)." (PMID 40626651, 2025). "Its targets do indeed play a role in controlling inflammatory pathways, responses to viral infections, and Toll-like receptor signaling (TNF signaling pathway, response to HBV, HCV, and EBV viruses, and Toll-like receptor pathways)." (PMID 40806764, 2025). "The study concluded that PCT was superior to all tested cytokines (TNF-α, IL-1β, IL-8) for distinguishing between bacterial and viral infections in this population." (PMID 40647525, 2025). "TNF-α acts as a frontline cytokine during viral infections and is produced by various cell types, notably macrophages and T cells." (PMID 41384113, 2025). "Its pathogenesis is multifactorial, involving direct viral infection of lymphocytes, cytokine-induced suppression and apoptosis—particularly mediated by IL-6 and TNF-α—bone marrow suppression, and redistribution of lymphocyte to inflamed tissues." (PMID 40700325, 2025). "In contrast to ubiquitin, FAT10 expression is specifically induced by the pro-inflammatory cytokines TNF and IFNγ, which are predominantly secreted by CTLs during viral infection." (PMID 40821782, 2025). "KEGG pathway analysis further indicated associations with necroptosis, viral infections (Influenza A, Measles, Hepatitis, Epstein-Barr virus), NOD-like receptor signaling, TNF signaling, apoptosis, and Th1/Th2 cell differentiation." (PMID 41180485, 2025). "In future, broad tests with other pro‐inflammatory stimuli, such as cytokines (IFNγ, TNFα, and IL‐1β) and virus infection, are suggested." (PMID 39455284, 2025).
viral infection (continued). "Studies have demonstrated that viral infections activate the innate immune system, leading to the production of inflammatory factors such as TNF-α and IFN-β." (PMID 40076601, 2025). "Necroptosis is a caspase-independent form of regulated necrosis induced by the recognition of tumor necrosis factor cytokines, metabolic stress, and virus infection." (PMID 40710498, 2025). "Viral infections of the airways induce mucosal injury that induces inflammatory cytokines such as TNF-α and interferons." (PMID 40617350, 2025). "Viral infection activates the immune system, leading to the release of inflammatory mediators such as proinflammatory cytokines (IL-6, IL-1β, and TNF-α) and eicosanoids (PG and LT)." (PMID 40580333, 2025). "IL-17-ativated DCs and viral infections trigger natural killer (NK) cells to secret pro-inflammatory cytokines (i.e. TNFα and IFNγ)." (PMID 40673003, 2025). "The next step was performing a classical ELISA for representative cytokines important for viral infection—IL-4, IL-5, IL-6, IL-10, IL-17, and TNF alpha." (PMID 40358160, 2025). "Several factors can induce necroptotic cell death, including the binding of tumor necrosis factor (TNF), cytokine and membrane receptors, interferons (IFNs) stimulation, or viral infection." (PMID 40217493, 2025). "TNF, a key inflammatory cytokine produced by macrophages, DCs, and T cells, exerts widespread effects on glucose metabolism during viral infections." (PMID 40453076, 2025). "TNFα is a key component of the primary immune response to viral infections, promoting cytokine production and contributing to inflammation." (PMID 41278481, 2025). "Tumor necrosis factor (TNF) is a key pro-inflammatory cytokine that plays a central role in orchestrating immune responses during viral infections." (PMID 41247592, 2025). "Other reported triggers include viral infections, silica exposure, and certain medications, such as hydroxyurea, statins, cyclophosphamide, and tumor necrosis factor (TNF) inhibitors." (PMID 40525043, 2025). "Individual differences in innate antiviral immunity exist, with endogenous interferons and TNF-α contributing to resistance against viral infections." (PMID 39772104, 2024). "During viral infection, TNF-α activates macrophages and dendritic cells, acts as a pyrogen in the development of fever, mediates hematopoiesis modulation, and is able to directly inhibit viral replication." (PMID 38256229, 2024). "High expression of pro-inflammatory molecules of IFN- and TNF-dependent pathways are detected during viral infections, for example, SARS-CoV-2, hepatitis B, and HIV-1." (PMID 38664730, 2024). "An increase in CCL5 levels in milk is expected because this chemokine is produced early during virus infection and can also be induced later in response to TNF-α and IFN-γ produced by CD4+ and CD8+ T cells, epithelial cells, fibroblasts, and platelets." (PMID 39867906, 2024). "As a result, circadian rhythm, the TNF signalling pathway, the virus infection pathway, and the NF-kappa B signalling pathway were enriched according to the KEGG analysis and the differential protein expression between the control and SD groups." (PMID 38491517, 2024). "On the other hand, the model group showed a significant increase (p ≤ 0.001) in all three inflammatory factors after virus infection, with TNF-a, IL-6, and iNOS levels at 144.11 ± 1.92 pg/mL, 417.62 ± 6.46 pg/mL, and 5.14 ± 0.25 pg/mL, respectively." (PMID 38426086, 2024). "Interferon-γ (IFN-γ) and tumor necrosis factor-α (TNF-α), both classified as Th1 cytokines, in conjunction with the bacterial product lipopolysaccharide (LPS) and viral infections, promote and enhance the polarization of M1 macrophages." (PMID 39749340, 2024). "IL-6 production is triggered in response to bacterial and viral infections and other cytokines such as IL-1β, TNF, and IFN-γ." (PMID 38362301, 2024).
viral infection (continued). "TNF-α triggers apoptosis and activates endothelium cells, hence enhancing the immunological response of fish against bacterial and viral infections and has a function in the immune response against bacterial and viral pathogens." (PMID 38720786, 2024). "This pathway is conventionally activated by TNF-α, IL-1, or byproducts of bacterial and viral infections." (PMID 39051372, 2024). "Its regulation is increased in bacterial infections in response to tumor necrosis factor-alpha, IL-1, and IL-6 and decreased in viral infections by interferon-gamma." (PMID 39724169, 2024). "These include proinflammatory M1-like macrophages, which produce TNF, IL-1β and IL-6, in the context of both metabolic disease and viral infection." (PMID 39107476, 2024). "Virus-induced secretion of cytokines, such as TNF and IL, contributes to innate immunity against viral infection." (PMID 38355571, 2024). "E-selectin remains largely inactive in resting endothelial cells, however, it is consistently expressed in response to inflammatory cytokines such as interleukin-1 (IL-1) bacterial lipopolysaccharide (LPS), viral infections, or tumor necrosis factor (TNF)." (PMID 39100681, 2024). "As expected, AZ reduced inflammatory cytokine expression, including TNF-α and IL-1β, and the translocation of NF-κB to the nucleus, which are all increased by viral infection." (PMID 38247540, 2024). "Both HIF-1α knockdown and treating the myocardial cell with QFPDD significantly reversed the increased inflammatory factors (IFN-β, IL-18, and TNF-α) mediated by viral infection." (PMID 38476329, 2024). "The innate immune system serves as the first line of defense against viral infections, with cytokines like TNF-α and IFITs playing critical roles in antiviral responses." (PMID 39769456, 2024). "PCT release is mediated by cytokines that increase in response to bacterial infections, such as tumor necrosis factor-α, interleukin 1β, and interleukin 6, and is suppressed by interferons released in response to viral infections." (PMID 38398159, 2024). "This study also identified typical pathways related to viral infections, including TNF-alpha NF-kappa B signaling and the activation of antiviral mechanisms by IFN-stimulated genes." (PMID 39066279, 2024). "In summary, we report that under inflammatory conditions, FAT10 is expressed and is phosphorylated by IKKβ in response to TNF and to viral infection." (PMID 37940187, 2024). "Following the influenza virus infection in the mice, significant increases in IL-6 and TNF-α concentrations in the serum indicated the activation of the immune system and the initiation of inflammatory responses to combat viral infection." (PMID 39410114, 2024). "In relation to virus infection, TNF-α signaling is an important driver of host antiviral defense leading to cell death and tissue destruction." (PMID 39009887, 2024). "Upon viral infection, previously elevated levels of TNF and subsequent neuroinflammation can either facilitate neurodegeneration or exert neuroprotection." (PMID 38339126, 2024). "Elevated levels of IL-6, INF-g, TNF-a, and IL17a mark an exacerbated inflammatory response and reflect the body’s attempt to combat the viral infection, with IL-6 being a pivotal mediator of fever and acute phase reactions." (PMID 39203987, 2024). "This systematic review identified that in vitro evaluation of proinflammatory cytokines released by microglia against viral infections, mainly the cytokines IL-6, TNF-α and IL-1β, was frequently compared to the evaluation of anti-inflammatory cytokines." (PMID 38349562, 2024). "Cytokine disturbances, especially increases in IL-6 and TNF-α, are common in both mental illnesses and viral infections, but are very unspecific." (PMID 39206043, 2024).
viral infection (continued). "IL-6 and TNF-α are key pro-inflammatory cytokines involved in the control of many viral infections, including WNV, but they also display an increase during WNND and appear as candidates for the cytokine-induced burden of illness." (PMID 38543749, 2024). "We demonstrated that viral infections lead to premature cellular senescence via paracrine induction of TNF-α." (PMID 37163429, 2023). "TNF-α (Tumor necrosis factor) is a cytokine secreted from T cells and macrophages that protects cells from viral infection and can kill those that have been infected with the virus." (PMID 38140542, 2023). "The loss of T cells has also been observed in various acute life-threatening viral infections, and the contribution of Fas/FasL and cytokines, such as TNFα, IL-6, IFN-γ, and IL-10, has been suspected." (PMID 38249467, 2023). "Additional enriched pathways included those related to IL-17, TNF, and NF-κB signaling pathways, among others related to viral infections." (PMID 38681774, 2023). "Miscellaneous causes include tuberculosis, trauma, uremia, aortic dissection, drugs (e.g., anticoagulant or anti-TNF alpha agent), and viral infection." (PMID 38264260, 2023). "This cytokine has been involved in the progression of virus infections and it is considered one of the most important cytokines in infections, along with IL-1 and TNF-α." (PMID 36730325, 2023). "Cytokines, such as IL6 and TNFα, have the ability to enhance immune responses against viral infections/vaccines." (PMID 36851183, 2023). "ILC1s express T-bet transcription factor and produce cytokines such as interferon (IFN)-γ and tumor necrosis factor (TNF)-α that are perilous against viral infections and cancers." (PMID 36675138, 2023). "In viral infections, TNF-α activation leads to the induction of hBD-2 via autocrine/paracrine mechanisms." (PMID 37003996, 2023). "More and more evidence suggests that Gal3 is involved in promoting various viral infections and enhancing pro-inflammatory cytokines such as IL-1, IL-6, and tumor necrosis factor α (TNFα)." (PMID 37958500, 2023). "It has been observed that GSDME is cleaved by caspase 3 to induce pyroptosis during viral infection and in tumors treated with chemotherapeutic drugs or following stimulation by tumor necrosis factor (TNF)." (PMID 37998332, 2023). "Viral infection can induce exogenous apoptotic pathways through PRR-dependent expression of programmed death ligand (including TNF-α)." (PMID 37627029, 2023). "Accumulating evidence suggests that Gal3 is involved in the promotion of various viral infections, and the enhancement of pro-inflammatory cytokines such as interleukin (IL)-1, IL-6, and tumor necrosis factor (TNF)-α." (PMID 37175823, 2023). "The Tumor Necrosis Factor (TNF) response to viral infection triggers the mitochondrial activity that oxidizes luminol in the presence of reactive oxygen species." (PMID 37031181, 2023). "Underlying chronic inflammation and/or viral infections create an immune suppressive TME in GC through the production of cytokines including IL-6, IL-11, TNF-α, and transforming growth factor (TGF)-ß35,36." (PMID 37577519, 2023). "In this study, we identified the ASFV pI10L as an inhibitor of virus-induced inflammatory responses following viral infection and treatment with TNF-α or IL-1β." (PMID 37607059, 2023). "Higher levels of inflammatory mediators like IL-25, IL-1β, IL-10, IL-5 and tumor necrosis factor (TNF) -α after viral infection were found in human nasal epithelial cell (HNEC) culture compared to controls." (PMID 38116043, 2023). "Growth factors and cytokines such as members of the interferon (IFN) and tumor necrosis factor (TNF) family are vital components of host immune activity that can shape viral infection-related processes and the subsequent development of fibrosis." (PMID 37122734, 2023).